SPARC (secreted protein acidic and cysteine rich)
Diseases named in the same sentence as SPARC in open-access papers (continued):
Sharing a sentence is not in itself a finding about the gene and the disease.
gastric cancer (continued). "Moreover, this recent study demonstrated that SPARC overexpression in M2 macrophages reduced M2-mediated functions including proliferation of gastric cancer cells, emphasizing the anti-tumorigenic role of SPARC in digestive cancers." (PMID 33466303, 2021). "SPARC is known to regulate the interactions between cells and their extracellular matrix, thereby modulating cell adhesion, proliferation and differentiation in diseases such as gastric cancer, lung cancer, idiopathic pulmonary fibrosis as well as in pterygia." (PMID 35174178, 2021). "In addition to tumor cells and fibroblasts, M2 macrophages have been shown to be a major source of SPARC in gastric cancer." (PMID 33466303, 2021). "Based on the studies above, the present study investigated the regulatory effects of endogenous SPARC on M2-mediated tumour growth promotion and the potential of macrophage-derived SPARC as a biomarker for the prognosis of gastric cancer and as a potential therapeutic target." (PMID 32226513, 2020). "The role of SPARC in gastric cancer has not been fully elucidated, although its diagnostic and prognostic value has been confirmed by multiple studies." (PMID 32848739, 2020). "In the follow-up study, the direct target of SPARC protein in gastric cancer will be found, and the in-depth mechanism of SPARC protein affecting gastric cancer will be explained, which will provide theoretical evidence for clinical treatment and targeted gene therapy." (PMID 32226513, 2020). "In the present study, we evaluated the expression level of SPARC in 76 gastric cancer samples." (PMID 32226513, 2020). "By immunohistochemical staining of SPARC in gastric cancer tissues, it was found that SPARC was mainly produced by tumour stroma in gastric cancer, and tumour-associated macrophages, tumour-associated fibroblasts and endothelial cells are the main sources 20-22." (PMID 32226513, 2020). "However, little research has been conducted to explore the role of macrophage-derived SPARC in tumour progression in gastric cancer." (PMID 32226513, 2020). "However, most studies have concentrated on tumour cell-derived SPARC, and the role of GCAF-derived SPARC in gastric cancer progression is poorly understood." (PMID 31139014, 2019). "Our previous work revealed that SPARC was mainly expressed in GCAFs in gastric cancer." (PMID 31139014, 2019). "The combination of GCAF-derived SPARC and pathway inhibitors may be a promising approach to reconsider in the adjuvant treatment of gastric cancer." (PMID 31139014, 2019). "Additionally, label-free quantification proteomics was used to identify the differentially expressed proteins and potential pathways in gastric cancer cells treated with GCAF-derived SPARC." (PMID 31139014, 2019). "Low expression of GCAF-derived SPARC indicated poor differentiation in gastric cancer." (PMID 31139014, 2019). "SPARC expression in GCAFs is a useful prognostic factor in patients with gastric cancer." (PMID 31139014, 2019). "Additionally, suppressing SPARC expression in GCAFs facilitated the phenotypic alteration of gastric cancer cells towards CD44+/CD24− cancer stem cell (CSC)-like cells." (PMID 31139014, 2019). "We hypothesize that SPARC participates the regulations of paracrine actions in GCAFs, and the alterations of paracrine factors in CM cause the activation of AKT/mTOR in gastric cancer towards aberrant proliferation and anti-apoptosis." (PMID 31139014, 2019). "Our data showed that knocking down SPARC in GCAFs promoted 5-FU resistance in gastric cancer cells." (PMID 31139014, 2019). "The expression of SPARC protein in CAF was suppressed by mucus-producing gastric cancer cells." (PMID 29156791, 2017). "However, in gastric cancer tissues, SPARC protein was highly co-localized with CD31 in the neo-vessels." (PMID 29156791, 2017).
gastric cancer (continued). "Therefore, it is advisable to concurrently enlarge the observed size of tumor tissue sections and to increase the number of cases to evaluate the true role of SPARC in the progression of gastric cancer." (PMID 29156791, 2017). "SPARC in the gastric cancer tissues was mainly expressed by stromal cells instead of cancer cells." (PMID 29156791, 2017). "The dynamic change of SPARC protein expression in gastric cancer tissue might reflect the real activity of fibrosis in anti-tumor process." (PMID 29156791, 2017). "Therefore, determining the cellular sources of SPARC protein in vivo and in vitro is critical to understand the diverse role of SPARC in tumor progression of patients with gastric cancer." (PMID 29156791, 2017). "Furthermore, mucus-producing adenocarcinomas, including signet ring cell carcinoma and mucinous adenocarcinoma, expressed much less SPARC protein compared with other pathohistological types of gastric cancer." (PMID 29156791, 2017). "A co-culture system was used to test whether gastric cancer cells affected the SPARC expression in fibroblasts." (PMID 29156791, 2017). "In addition, only 42.9% (24 out of 56 cases) of mucus-producing adenocarcinomas (e.g., signet ring cell and mucinous adenocarcinomas) were positive for SPARC staining, which was lower than any other pathohistological types of gastric cancer(P=0.002)." (PMID 29156791, 2017). "Moreover, the relationship of SPARC overexpression with gastric-cancer progression is further confirmed by our study using GSEA and MTT assay." (PMID 28053291, 2016). "Further more, a meta-analysis indicated the negative prognostic value of SPARC expression in patients with gastric cancer, with the relative risk of OS (RR = 1.78, 95% CI: 1.52–2.09, Z = 7.10, p = 0.43)." (PMID 26731428, 2016). "We evaluated expression of SPARC in seven human gastric cancer cell lines." (PMID 22957090, 2012). "We evaluated expression of SPARC in several human gastric cancer cell lines." (PMID 22957090, 2012). "We confirmed that SPARC is upregulated in gastric cancer compared to benign gastric mucosa." (PMID 22929309, 2012). "In summary, the growth inhibition of gastric cancer by SPARC seems to be mediated through its suppression effects on MMP-7 and VEGF expressions, which may in turn inhibit microvessel infiltration into tumours." (PMID 22957090, 2012). "Therefore, in gastric cancer xenografts, SPARC expression is negatively correlated with angiogenesis." (PMID 22957090, 2012). "Downregulation of SPARC expression didn't induce cell cycle arrest in gastric cancer cells." (PMID 20525171, 2010). "SPARC expression was evaluated in a panel of human gastric cancer cell lines." (PMID 20525171, 2010). "We first evaluated the endogenous expression of SPARC in several human gastric cancer cell lines." (PMID 20525171, 2010). "Therefore, the aim of the present study was to characterize SPARC functions in gastric cancer cells and explore its possibly carcinogenic mechanism." (PMID 20525171, 2010). "It is exciting that therapy targeting the SPARC subunit may be a useful approach to suppress gastric cancer growth." (PMID 20525171, 2010). "The knowledge about SPARC functions in gastric cancer cells is still sparse." (PMID 20525171, 2010). "We found that SPARC siRNA could induce gastric cancer cell apoptosis and simultaneously reduce the ratio of Bcl-2 to Bax." (PMID 20525171, 2010). "We had analysed the serum SPARC expression in 20 gastric cancer patients by the Western blot." (PMID 15558074, 2004). "SPARC overexpression in primary tumor tissues has since been demonstrated to be significantly associated with poor prognosis in melanoma, ESCC, non-small cell lung cancer (NSCLC), breast cancer, gastric cancer (GC), PDAC, CRC, and leukemia, and prognosis was poor in case of its stromal expression." (PMID 38892190, 2024). "SPARC may support the invasion, metastasis, and angiogenesis of gastric cancer cells." (PMID 37577749, 2023).
gastric cancer (continued). "SPARC may participate in gastric cancer by affecting the tumor microenvironment transfer." (PMID 37577749, 2023). "Human gastric cancer cell invasion and growth may be inhibited by the downregulation of SPARC." (PMID 37577749, 2023). "Thus, the concrete mechanism of SPARC in gastric cancer needs further investigation." (PMID 32848739, 2020). "However, some oncologists have shown that SPARC is mostly produced by gastric cancer-associated fibroblasts rather than gastric cancer cells." (PMID 32848739, 2020). "As the main source of SPARC, GCAFs also play an important role in the tumour microenvironment, and our previous work suggested that activated GCAFs contribute to the malignant phenotype and 5-fluorouracil (5-FU) resistance via paracrine action in gastric cancer." (PMID 31139014, 2019). "To test these hypotheses, we tested expression of SPARC in seven gastric cancer cell lines." (PMID 22957090, 2012). "The primary function of SPARC in angiogenesis of gastric cancer cell lines remains unclear." (PMID 22957090, 2012). "The function of SPARC in gastric cancer cells remains unclear." (PMID 22957090, 2012). "Thus, SPARC siRNA can decrease gastric cancer invasion in vitro." (PMID 20525171, 2010). "Therefore, we tested our hypotheses that SPARC may be a key molecule in gastric cancer invasion, and that targeting SPARC may present a novel therapeutic strategy for anti-invasion of gastric cancer." (PMID 20525171, 2010). "We investigated whether SPARC siRNA could induce cell death in gastric cancer cell lines." (PMID 20525171, 2010). "We investigated whether SPARC siRNA could decrease the survival of gastric cancer cells." (PMID 20525171, 2010). "qPCR analysis revealed that the significant expressions of SPARC, EFEMP1, RGS5 and SERPINE1 were significantly upregulated in gastric cancer tissues compared to the normal tissues." (PMID 41584584, 2025). "The key genes included in the LASSO-Cox regression model (including SPARC, EFEMP1, RGS5 and SERPINE1) were significantly upregulated in gastric cancer compared to the normal tissue." (PMID 41584584, 2025). "There are multiple known gene targets for miR-29c-3p, which include Mesoderm-specific transcript (MEST) and Secreted protein acidic and rich in cysteine (SPARC), which are known to be involved with colorectal and gastric cancer." (PMID 41465589, 2025). "I with a logFC >1, we generated a gene signature of iGC stage progression (intestinal-type gastric cancer progression signature - iGCPS), composed of APOD, COL1A2, GEM, FSTL1, LUM and SPARC." (PMID 39563861, 2024). "In the HPA database, the protein expression of the four model genes EDNRA, SPARC, THBSI, and VCAN was higher in gastric cancer tissues compared with normal tissues." (PMID 39040110, 2024). "Next, to further validate the roles of FIRGs in the development of gastric cancer, we silenced GPX3, SPARC and NOX4 in gastric cancer cell lines MGC803 and MKN45 to examine the effects on the cell viability, proliferation and migration/invasion." (PMID 38021154, 2023). "Eight out of 38 upregulated genes in gastric cancer (ASPN, COL1A1, COL1A2, COL3A1, COL5A1, FAP, FN1, and SPARC) overlapped with the CAF markers list (circos plot on the left)." (PMID 35739492, 2022). "The results of in vivo imaging experiments showed that SPARC-overexpressing M2 and BGC-823 gastric cancer cells were simultaneously injected subcutaneously into nude mice, and their growth rate was much lower than that of the control group." (PMID 32226513, 2020). "Another study showed a significant difference in the SPARC levels in tumor tissue between gastric cancer and ESCC (15% vs. 34%), suggesting SPARC as a potential novel therapeutic target." (PMID 31950035, 2019). "We herein identified a large number of genes associated with the ECM and cell adhesion to be differentially expressed in intestinal gastric cancer, including TIMP1, MMP7, FN1, SPARC, LUM and BGN, which were upregulated." (PMID 29484116, 2018).
gastric cancer (continued). "Downregulating of SPARC by siRNA-mediated knocking down its gene inhibits growth and invasion of MGC803 and HGC27 gastric cancer cells." (PMID 26731428, 2016). "Then, to assess the effect of altered SPARC on gastric cancer cells, we established a BGC-SP clone which overexpressed SPARC and a HGC-sh clone in which the endogenous SPARC was knocked down." (PMID 22957090, 2012). "Thus, targeting of SPARC could be an effective therapeutic approach against gastric cancer." (PMID 20525171, 2010). "Small interfering RNA-mediated knockdown of SPARC in MGC803 and HGC 27 gastric cancer cells dramatically decreased their invasion." (PMID 20525171, 2010). "Knockdown of SPARC was also observed to significantly increase the apoptosis of MGC803 and HGC 27 gastric cancer cells compared with control transfected group." (PMID 20525171, 2010). "Three of these are known to be involved in gastric cancer: MMP7, SPARC, and SOD2, and the other four have no such reported associations (INHBA, IGFBP7, NEK6, and LUM)." (PMID 18827816, 2008). "For instance, high levels of SPARC induced stemness in endometrial and hepatocellular carcinomas but not in gastric cancer cells." (PMID 38562556, 2024). "Moreover, the MSLN, SPP1, THBS2, SPARC, FN1, IGFBP7, VCAN were up-regulated in gastric carcinoma samples, while FGA was down-regulated." (PMID 36842141, 2023). "Also, the invasion and proliferation ability was inhibited in SPARC knockdown MGC803 and HGC 27 gastric cancer cell lines, which demonstrated the tumor-promoting activity of SPARC." (PMID 35368700, 2022). "Hence the module analysis strengthened the connection of the six CAF markers: COL1A1, COL1A2, COL3A1, COL5A1, FN1 and, SPARC, with the 3 KEGG pathways: ECM-receptor interaction, focal adhesion and, PI3K-Akt signaling pathway in gastric cancer." (PMID 35739492, 2022). "The results showed that 8 up-regulated genes (FN1, COL3A1, FBN1, BGN, COL5A2, THBS2, COL5A1 and SPARC) and 1 down-regulated gene (ATP4A) may be the central genes in gastric cancer." (PMID 32742441, 2020). "This provides a guarantee for future SPARC-targeted treatment on gastric cancer, because it only attenuates the proliferation of gastric cancer cells, but does not affect the proliferation of normal gastric mucosa." (PMID 32226513, 2020). "SPARC suppresses angiogenesis by downregulating the expression of VEGF and MMP-7 in gastric cancer." (PMID 32226513, 2020). "In the present study, the conditioned medium from GCAFs with SPARC knockdown could arouse AKT expression, and lead to the increasing abilities of stemness and 5-FU resistance in gastric cancer cell lines." (PMID 31139014, 2019). "The 3D tumour growth and 5-FU resistance abilities of gastric cancer cells were elevated after treatment with GCAFs with SPARC knockdown relative to these abilities in negative control cells." (PMID 31139014, 2019). "Positive SPARC expression was identified in 63.3% of gastric cancer tissues and 28.2% of non-cancerous tissues." (PMID 29156791, 2017). "Higher positivity of SPARC was observed in gastric cancer tissues than non-cancerous gastric tissues (P=0.000)." (PMID 29156791, 2017). "The positivity of SPARC was related to age (P=0.032), tumor location (P=0.018), depth of tumor invasion (P=0.011), nodal metastasis (P=0.023), TNM stage (P=0.034), the differentiation degree (P=0.006) and pathological type (P=0.002) of gastric cancer." (PMID 29156791, 2017). "In vitro experiments indicated that human gastric cancer cells, especially human mucus-producing gastric adenocarcinoma derived cells (MKN-45), could potentially inhibit the expression of SPARC in fibroblasts." (PMID 29156791, 2017). "In this study, 365 gastric cancer patients and 39 non-cancerous samples were enrolled to investigate the positivity of SPARC protein on the large tissue sections instead of using tissue microarray." (PMID 29156791, 2017).
gastric cancer (continued). "We found that the positivity of SPARC protein in gastric cancer tissues was much higher than that in non-cancerous tissues, which is also reported by other research." (PMID 29156791, 2017). "The estimated survival time of gastric cancer patients without SPARC expression was 45.4 months, which was longer than patients in the SPARC-positive group (42.7 months)." (PMID 29156791, 2017). "The cumulative survival results suggested that the SPARC expression in tumor microenvironment would not significantly affect the prognosis of the patients with gastric cancer." (PMID 29156791, 2017). "The status of distant metastasis and cancer embolus in the stromal vessels did not affect the positivity of SPARC in gastric cancer tissue." (PMID 29156791, 2017). "Positive expression of SPARC protein was observed in 28.2% of the non-cancerous tissue sample (11 out of 39 individuals) and 63.3% of the gastric cancer tissue (231 out of 365 patients), respectively." (PMID 29156791, 2017). "The positivity of SPARC staining in gastric cancer tissues was significantly higher than that in non-cancerous tissues (Pearson’s Chi-square test, P=0.000)." (PMID 29156791, 2017). "However, whether secreted protein acidic and rich in cysteine (SPARC) expression changes after chemotherapy in gastric cancer (GC) is unclear." (PMID 25859409, 2015). "Some immunohistochemical studies collectively reported an up-regulation of SPARC in gastric cancer compared with nonneoplastic mucosa." (PMID 20525171, 2010). "We measured the capacity of gastric cancer cells to invade through Matrigel, an artificial extracellular matrix, after transfection with a non-targeting control siRNA or SPARC siRNA." (PMID 20525171, 2010). "We measured the capacity of gastric cancer cells to invade through Matrigel, an artificial extracellular matrix, after transfection with SPARC siRNA or a non-targeting control siRNA." (PMID 20525171, 2010). "Gastric cancer patients with high expression levels of FN1 (HR = 1.54, P < 0.05), MAC25 (HR = 1.48, P < 0.05), THBS2 (HR = 1.55, P < 0.05), VCAN (HR = 1.32, P = 0.0031), SPARC (HR = 1.42, P < 0.05), MSLN (HR = 1.28, P = 0.0066), and FGA (HR = 1.37, P < 0.05) had shorter survival time." (PMID 36842141, 2023). "SPARC positivity in gastric cancer tissue was higher than in non-cancerous gastric tissue." (PMID 37577749, 2023). "The topmost molecular network in the intestinal subtype on IPA network analysis showed increased expression of SULF1, HGF, SPARC, SERPINH1, and IGFBP7, which have been shown to contribute to the growth and survival of tumor cells, tumor invasion, metastasis, and poor survival in gastric cancer." (PMID 34885041, 2021). "The survival curves showed that the overall survival rate of macrophage-derived SPARC patients with low expression of gastric cancer was lower than that of patients with high expression of SPARC, but the difference was not statistically significant (χ2=3.106, P = 0.078)." (PMID 32226513, 2020). "It was supposed that gastric cancer cells could escape the nonspecific apoptosis induced by CAF through suppressing the endogenous expression of SPARC in fibroblasts." (PMID 29156791, 2017). "No endogenous SPARC protein was found in gastric cancer cell lines (AGS and MKN-45)." (PMID 29156791, 2017). "Also, we observed that the distribution of SPARC positive cells in gastric cancer tissue was not equal." (PMID 29156791, 2017). "The up-regulation of SPARC in gastric cancer tissue is not restricted to the gene level." (PMID 29156791, 2017). "Therefore, in this study, we hypothesized that SPARC might modulate proliferation and angiogenesis by regulating VEGF and MMP-7 expressions in gastric cancer cells." (PMID 22957090, 2012). "However, the molecular mechanisms responsible for the oncogenesis of SPARC in gastric cancer is not entirely understood." (PMID 20525171, 2010).